PCSK9 (proprotein convertase subtilisin/kexin type 9)
Diseases named in the same sentence as PCSK9 in open-access papers (continued):
Sharing a sentence is not in itself a finding about the gene and the disease.
Stroke (continued). "Addressing this question, data from clinical trial FOURIER (Further Cardiovascular Outcomes Research with PCSK9 Inhibition in Subjects with Elevated Risk) have demonstrated a significant relative risk reduction of MI (HR 0.73; 95% Cl 0.65 − 0.82) and stroke (HR 0.79; 95% Cl 0.66 − 0.95)." (PMID 38907775, 2025). "For patients at very high or high CV risk who are not responsive to or are intolerant of statins, ezetimibe, alone or in combination with statins, and PCSK9 inhibitors may reduce stroke risk." (PMID 39713216, 2024). "Subanalysis of the Further Cardiovascular Outcomes Research With PCSK9 Inhibition in Subjects With Elevated Risk study investigated the efficacy of evolocumab vs. placebo for reducing CV events in a subset of statin-treated patients with prior stroke." (PMID 38288054, 2023). "Each 1 mmol/L decrease in LDL-C level was associated with a significantreduction of all stroke risk by 23.5% (slope = 0.235; [95% CI: 0.007–0.464]).PCSK9 inhibitors are proven to have the greatest ability to reduce stroke ratesamong various lipid-lowering drugs." (PMID 39076187, 2022). "Accordingly, we conducted the current meta-analysis to add substantive new data and insights into the predictive ability of circulating PCSK9 level in terms of major adverse cardiovascular events (MACEs), stroke, and all-cause mortality from the eligible prospective studies." (PMID 33738300, 2021). "Two-stage analysis among postmenopausal women generates novel hypotheses about the interaction between F13A1 and PCSK9 genomic regions and the effects of hormonal exposures on postmenopausal stroke risk for subsequent independent validation." (PMID 22794791, 2012). "Two-stage analysis among postmenopausal women generates novel hypotheses concerning the F13A1 and PCSK9 genomic regions and the effects of hormonal exposures on postmenopausal stroke risk for subsequent independent validation." (PMID 22794791, 2012). "Nevertheless, it remains controversial whether PCSK9 variants associates with risk of stroke." (PMID 33738300, 2021). "Finally, statistical tests for detecting publication bias in pooling the effect estimates of PCSK9 and all-cause mortality and stroke may be potentially unreliable due to less than the recommended minimum number of 10 studies analyzed." (PMID 33738300, 2021). "In addition, PCSK9 gene variants have been associated with stroke that may either be linked to PCSK9-dependent vascular inflammation or LDL-C." (PMID 33364976, 2020). "Overall, these findings suggest that the use of PCSK9 inhibitors in conjunction with statins is promising for improving the clinical outcomes of stroke patients with sICAS in the future." (PMID 41601579, 2026). "This intervention reduced infarct volume by 35–40% and improved functional recovery, underscoring the therapeutic potential of PCSK9 inhibition in stroke management." (PMID 41190281, 2025). "Collectively, this synthesis establishes a foundational framework for positioning PCSK9 inhibitors as transformative agents in stroke therapeutics and paves the way for precision neurovascular medicine." (PMID 41190281, 2025). "The anti-inflammatory potential of PCSK9 inhibitors was further confirmed in preclinical stroke models." (PMID 41368357, 2025). "This strongly supports the potential of PCSK9 inhibitors as a preventive therapy for stroke, particularly in individuals with hyperlipidemia." (PMID 40863347, 2025). "These approaches will elucidate the therapeutic relevance of PCSK9 inhibition in stroke pathophysiology." (PMID 41190281, 2025). "While the impact of Lp(a) reduction on stroke prevention remains uncertain, the use of a PCSK9 inhibitor in this case was based on its dual lipid-lowering properties and its potential role in secondary prevention and risk modification." (PMID 40671719, 2025). "By mitigating IL‐6 and TNF‐α‐mediated inflammation, PCSK9‐i highlight potential immunometabolic therapies for stroke and neurodegeneration." (PMID 41190281, 2025).
Stroke (continued). "Proprotein convertase subtilisin/kexin type 9 (PCSK9) has become a key modulator of plasma LDL-C levels and stroke risk in the lipid metabolism pathway." (PMID 40863347, 2025). "The stroke effect was smaller, potentially due to the slower action of PCSK9 inhibitors on plaque stability." (PMID 40918505, 2025). "Future multi-center studies with larger sample sizes and longer follow-up periods are necessary to validate our results and explore the long-term benefits and risks of combined PCSK9 inhibitors and statin therapy in stroke patients." (PMID 39762992, 2025). "It was reported previously that monoclonal antibodies that target PCSK9 (such as evolocumab and alirocumab) can alleviate vascular events, including stroke (Castilla-Guerra, Fernandez-Moreno & Rico-Corral, 2019)." (PMID 39157774, 2024). "This regimen also ranked first in reducing the incidence of stroke recurrence, followed by PCSK9 inhibitors plus statins (SUCRA: 0.60) and statins alone (SUCRA: 0.40)." (PMID 37881090, 2024). "Acute coronary syndromes, coronary interventions, stroke, and cardiac arrest are more prevalent in patients with rejected or abandoned PCSK9 inhibitor prescriptions compared to those with paid PCSK9 inhibitor prescriptions." (PMID 39064199, 2024). "The addition of PCSK9 inhibitors to high-dose statin has been shown to reduce the occurrence of stroke, MI, and cardiovascular death in patients with vascular diseases or high-risk features." (PMID 38817546, 2024). "SMR association between expression of gene HMGCR, PCSK9, NPC1L1 or APOB and stroke and its subtypes." (PMID 37528862, 2023). "With the birth of PCSK9 inhibitors and their gradually popularized use, their benefits in the therapy of stroke have been progressively discovered." (PMID 38273837, 2023). "Compared to placebo, PCSK9 inhibitors (alirocumab and evolocumab) reduced the risk of CVD, MI, stroke (combination of ischemic and hemorrhagic events), and all-cause death (high-certainty evidence) (for alirocumab)." (PMID 36895542, 2023). "Apart from statins, other lipid-lowering drugs (ezetimibe, proprotein convertase subtilisin/kexin type 9 (PCSK9) inhibitors) are recommended in a group of patients for stroke prevention." (PMID 37762627, 2023). "The SMR method was conducted to assess the association between the expression of HMGCR, PCSK9, NPC1L1, and APOB and stroke outcome." (PMID 37528862, 2023). "Statins, ezetimibe, and PCSK9 inhibitors should be administered to stroke patients for secondary prevention." (PMID 37109734, 2023). "IVW-MR association between LDL cholesterol mediated by gene HMGCR, PCSK9, NPC1L1, or APOB and stroke and its subtypes." (PMID 37528862, 2023). "In a systematic analysis of the PCSK9 locus, we identified genetic associations with SBPsdj, WHRadjBMI, VTE, stroke, mood instability and neuroticism score, with the same signal (indicated by LD r2 = 0.98) associated with WHRadjBMI and mood instability." (PMID 35501368, 2022). "Between 62 % and 67 % of US adults with a history of CHD, MI and stroke were estimated to be recommended add-on lipid-lowering therapy and between 2.9 % and 4.0 % of these populations were taking ezetimibe or a PCSK9 inhibitor." (PMID 37168932, 2022). "Given the continued clinical benefit of early initiation of statin treatment in patients with acute coronary syndrome or stroke, the optimal timing of treatment with PCSK9 inhibitors should be investigated in dedicated outcome assessment trials." (PMID 35890138, 2022). "Accordingly, LDL-cholesterol-lowering treatment by statins, ezetimibe, and/or PCSK9 inhibitors is preferentially indicated for secondary prevention of stroke so far." (PMID 35187103, 2021). "Genetically-instrumented lower PCSK9 concentration was associated with a lower risk of CHD, HF, and CKD, and additionally with any stroke, ischemic stroke, AF, MS, as well as an increased risk of asthma and AD18." (PMID 34561430, 2021).
Stroke (continued). "Additional well-designed studies are warranted to further investigate the correlations between PCSK9 concentration and stroke and mortality." (PMID 33738300, 2021). "Animal studies have found that alirocumab treatment rescues liver phenotypes in an alcohol-fed rat model and peripheral PCSK9 inhibition prevents astrocyte and microglial activation and neuroinflammation in a rat model of stroke." (PMID 33919550, 2021). "In contrast, lower PCSK9 concentration is anticipated to decrease the risk of CHD, heart failure, atrial fibrillation, chronic kidney disease, multiple sclerosis, and stroke, while potentially increasing the risk of Alzheimer’s disease and asthma." (PMID 34561430, 2021). "Conversely, inhibiting PCSK9 in a rat model of stroke resulted in attenuated Aβ aggregation, suggesting PCSK9 promotes plaque formation." (PMID 32595449, 2020). "A study of evolocumab, a monoclonal antibody against PCSK9, showed that stroke is significantly reduced in the group that received the drug compared to the group that received placebo in a similar magnitude to statins when treated over a period of 2 years." (PMID 32595449, 2020). "The incidence of all CV events and stroke was significantly greater in patients with tertile 3 PCSK9." (PMID 31963408, 2020). "We analyzed data from 10,924 Black participants tested for PCSK9 LOF variants in the REasons for Geographic and Racial Differences in Stroke (REGARDS) cohort." (PMID 30726226, 2019). "By contrast, PCSK9-inhibitor therapy (as with statin therapy and ezetimibe) has been shown to reduce the risk of CHD and stroke comparably." (PMID 29020353, 2018). "An exciting prospect is the introduction of proprotein convertase subtilisin/kexin type 9 (PCSK9) inhibitors which, when added to statins, seem to result in a more effective reduction of LDL-C192,193, with potential beneficial effect in stroke risk reduction." (PMID 29263784, 2017). "In addition, PCSK9 inhibitors has been observed in reducing early recurrent stroke in patients with sICAS during a 1-month follow-up." (PMID 41601579, 2026). "Additionally, the adjunctive use of PCSK9 inhibitors has been shown to reduce early recurrent stroke in patients with sICAS over a 1-month follow-up period." (PMID 41601579, 2026). "For instance, PCSK9 mutations affect LDL-C levels, and loss-of-function mutations are associated with a lower risk of stroke, indicating that PCSK9 inhibitors may be used therapeutically to prevent strokes." (PMID 40863347, 2025). "An earlier meta-analytic study of 67 RCTs including 259,429 participants with PCSK9 inhibitors plus statin confirmed the significantly reduced risk of non-fatal MI (RR 0.82; 95% CI 0.72–0.93, p = 0.003) or stroke (RR 0.74; 95% CI 0.65–0.85, p < 0.001)." (PMID 38907775, 2025). "By contrast, acute cerebrovascular injury shows a more consistent pattern in animals: across rodent stroke models, lowering PCSK9 before or around the ischemic insult reduces infarct size and improves functional recovery, consistent with an anti-inflammatory, tissue-protective effect." (PMID 41002444, 2025). "The ongoing VESALIUS-CV trial (NCT03872401) will provide five-year safety data on the effect of PCSK-9 inhibitors on cardiovascular outcomes in lower-risk patients without a history of MI or stroke." (PMID 40648946, 2025). "Furthermore, fine-mapping efforts via deep-coverage sequencing confirmed that the PCSK9 variant rs11591147 lowers LDL-C and confers stroke protection, reinforcing its status as a prime therapeutic target." (PMID 40863347, 2025). "Clinical trials have demonstrated the efficacy and safety of PCSK9 inhibitors in stroke prevention." (PMID 38789568, 2024). "Meta-analysis of recent randomized clinical trials revealed promising results regarding the efficacy of PCSK9 inhibitors reducing the incidence of stroke by 25%, highlighting the potential of PCSK9 inhibitors as valuable additions to the current armamentarium for cerebrovascular risk reduction." (PMID 39764289, 2024).
Stroke (continued). "In addition, recent results have confirmed the efficacy of PCSK9 inhibitors in reducing major cardiovascular events and have also shown the benefit of treatment with PCSK9 inhibitors in schematic stroke." (PMID 38988669, 2024). "Thus, PCSK9 inhibitors have demonstrated beneficial effects on brain function in stroke, myocardial ischemia/reperfusion injury, and insulin resistance-related cognitive impairment models." (PMID 39157774, 2024). "In this study, we retrospectively investigated patients who underwent MT at a regional stroke center to assess whether the early administration of PCSK9 inhibitors is effective in improving the functional outcomes after acute ischemic stroke." (PMID 38817546, 2024). "A series of experiments conducted in rat stroke models found a negative association between the expression of PCSK9 and the formation of amyloid plaques." (PMID 37586604, 2023). "Many studies have shown that intensive lipid-lowering therapy with a high dose of statins or a combination of statins with ezetimibe/proprotein convertase subtilisin/kexin type 9 (PCSK9) inhibitors prevents recurrent stroke after transient ischemic attack and ischemic stroke." (PMID 37653796, 2023). "Current clinical trials have confirmed the use of PCSK9 inhibitors to treat and prevent stroke." (PMID 38273837, 2023). "A pooled analysis that included both FOURIER and ODYSSEY OUTCOME studies, identified a reduced risk of stroke in patients with or without a previous stroke who received PCSK-9 inhibitors." (PMID 36142135, 2022). "This systematic analysis of the PCSK9 locus for effects on CMD and SMI-related traits in UK Biobank identified signals associated with four cardiometabolic traits (VTE, stroke, SBPadj and WHRadjBMI) and two psychological traits (mood instability and neuroticism)." (PMID 35501368, 2022). "Large-scale and well-designed prospective population-based studies are required to investigate further whether an increased level of PCSK9 will have predictive value for stroke and its subtypes." (PMID 33738300, 2021). "We analyzed circulating PCSK9 to elucidate the relationship between PCSK9 and stroke further." (PMID 33738300, 2021). "In patients with a history of ASCVD and statin therapy, PCSK9 inhibitors significantly lowered plasma LDL-C levels and the risk of cardiovascular (CV) events (e.g., CV death, myocardial infarction, stroke) compared to the control group with only the standard therapy." (PMID 33919550, 2021). "The association between PCSK9 and stroke showed an adverse but not statistically significant difference (HR: 0.95, 95 CI% 0.55–2.82)." (PMID 31711505, 2019). "Recent studies have suggested that the beneficial effects of PCSK9 inhibitors on stroke risk may be independent of LDL-C and Lp(a) levels." (PMID 40354375, 2025). "In addition, it is worth exploring whether the combination of PCSK9 inhibitors with immunomodulatory drugs such as IL-6 antagonists synergistically ameliorates immune disorders after stroke." (PMID 41368357, 2025). "Likewise, PCSK9 inhibitors have been reported to reduce the incidence of stroke by 25%." (PMID 39713216, 2024). "Furthermore, the use of proprotein convertase subtilisin/kexin type 9 (PCSK9) inhibitors could prevent stroke by reducing LDL-C." (PMID 37684620, 2023). "In a recent meta-analysis of 67 randomized controlled trials (RCTs) including 259,429 participants PCSK9 inhibitors plus statin significantly reduced the risk of non-fatal MI (RR 0.82, 95% CI 0.72–0.93, p = 0.003) or stroke (RR 0.74, 95% CI 0.65–0.85, p < 0.001)." (PMID 33262707, 2020). "While low PCSK9 and LDL-C levels may not reduce baseline stroke risk, PCSK9 inhibitors (PCSK9i) help reduce stroke incidence in patients with high cholesterol and high risk of cardiovascular disease." (PMID 32595449, 2020).
Stroke (continued). "However, there did not appear to be an association of rs11591147 with stroke risk in the initial studies of PCSK9 among individuals of African American or European ancestry, although the number of strokes observed was small." (PMID 29020353, 2018). "Further analyses showed significant stroke risk interaction between these F13A1 SNPs and estrogen plus progestin (E+P) treatment for ischemic stroke and for ischemic and hemorrhagic stroke combined, and suggested interactions between PCSK9 SNPs with either E+P or estrogen-alone treatment." (PMID 22794791, 2012). "Other PCSK9 GOF mutants (F216L, R357H, and R215H) were described in different FH French families with tendon xanthomas, CHD, premature MI, and stroke." (PMID 38907775, 2025). "Finally, it was investigated whether PCSK9 plays a role in stroke." (PMID 33364976, 2020). "Future work is also needed to explore the systemic vs. localized brain effects of PCSK9 monoclonal antibodies and if or to what extent these antibodies cross the BBB during disease states including AD, stroke, and chronic inflammatory brain diseases." (PMID 32595449, 2020). "In fact, previous studies have provided divergent results regarding whether PCSK9 gene is associated with high risk of stroke and only one study evaluated the relationship between circulating PCSK9 and stroke, and found non-significant association in large cohorts." (PMID 31711505, 2019). "In addition to conventional lipid-lowering therapies, novel agents such as PCSK9 inhibitors and inclisiran have been shown to exert anti-inflammatory and endothelial-protective effects, which could potentially mitigate PSD risk in dyslipidemic stroke survivors." (PMID 41031193, 2025). "Evolocumab, a monoclonal antibody that inhibits PCSK9, not only lowers LDL-C levels but also reduces the occurrence of major adverse cardiovascular events in individuals with established ASCVD, which includes prior MI, stroke, and peripheral vascular disease." (PMID 39770423, 2024). "Interestingly, a Mendelian randomization study of the PCSK9 LOF variant rs11591147 (R46L, G/T) in 337,536 individuals from the UK Biobank found the T allele was protective against ischemic stroke in the hypothesis-driven set and a nominally significant association with stroke in the full data set." (PMID 32595449, 2020). "Despite the negative results, they suggest that PCSK9 inhibitors may have a threshold effect on the modulation of the immune response after stroke, which needs to be further validated in a larger cohort combining transcriptomics with functional immunoassays." (PMID 41368357, 2025). "Fifth, exploring combination strategies involving statins and non-statin agents (e.g., PCSK9 inhibitors, ezetimibe) in statin-resistant individuals may help optimize outcomes in precision-guided, post-stroke lipid management." (PMID 41295435, 2025). "Therefore, considering PCSK9 inhibitors for a stroke patient can be another option if the LDL-C goal is not reached or optimum intensity of statins cannot be administered due to side effects." (PMID 37109734, 2023). "Studies of other functional PCSK9 variants that produce large effects on PCSK9 and LDL-C levels (e.g. mutations in Y142X or C679X associated with life-long differences in LDL-C levels of about 1 mmol/L) have not detected associations with stroke." (PMID 29020353, 2018). "Similar conclusions regarding stroke were drawn from the FOURIER trial, investigating the PCSK9 inhibitor evolocumab added to statin therapy in 27 564 patients with stable, established, atherosclerotic cardiovascular disease, including 19.4% with a history of nonhemorrhagic stroke." (PMID 31707788, 2019).
Stroke (continued). "Because no ASCVD outcomes as defined above were reported for the PCSK9 mAb alirocumab trial, ODYSSEY OUTCOMES, a sensitivity analysis with the trial’s primary endpoint of death, nonfatal MI, fatal or nonfatal stroke, or hospitalized unstable angina is reported in S3 Fig." (PMID 33119602, 2020).